STAT1 (signal transducer and activator of transcription 1)
Diseases named in the same sentence as STAT1 in open-access papers (continued):
Sharing a sentence is not in itself a finding about the gene and the disease.
viral infection (continued). "Notably, STAT1 ubiquitination at lysine 525 was induced upon viral infection, but this modification was suppressed by PTIR1." (PMID 41213949, 2025). "Furthermore, comprehensive functional screening identified fumarylacetoacetate hydrolase (FAH) as a previously unidentified candidate that contributes to the control of viral infection independently of STAT1." (PMID 40048440, 2025). "Simultaneously, the levels of STAT1 mRNA and protein exhibited a significant increase, which was consistent with the expression trend of the Erns protein observed in both the transfection group and virus infection group." (PMID 40001503, 2025). "Immunofluorescence analysis further supported the hypothesis that G3BP2 increasingly binds to STAT1 in the cytoplasm during virus infection." (PMID 40626722, 2025). "Moreover, an augmented level of STAT1 phosphorylation suggested transcriptional activation of ISGs, which are crucial for governing responses to viral infection." (PMID 40665421, 2025). "TBK1 is known to activate STAT1 through IRF3/7 in response to viral infections." (PMID 39415484, 2025). "The results obtained from these two independent studies showed that the immune response to the live attenuated yellow fever vaccine is preceded by an orchestrated overexpression of key transcription factors, including STAT1 and IRF7, which can elicit a broad and long-lasting immune response." (PMID 38932312, 2024). "Further, interactions between STAT1 and interferons highlight the critical role of STAT1 in the regulation of interferon-stimulated genes, because interferons are key cytokines in the immune response to viral infections." (PMID 39040605, 2024). "The importance of STAT1/2 in viral infection has been well-illustrated." (PMID 36982532, 2023). "Serine phosphorylation of STAT1 is required for the body's resistance to viral infection." (PMID 37143582, 2023). "The phenotype of STAT1 and STAT2 deficiency is in part reflected in mice, in that both Stat1–/– and Stat2–/– mice display increased susceptibility to viral infection with increased mortality and indications of inflammation, although formal comparisons are challenging." (PMID 36976641, 2023). "Stat1 is a key immune stimulator that impacts interferon activation during viral infections." (PMID 38133335, 2023). "The DN STAT1 alleles do not lead to a predisposition to viral infections, which can be explained by an unaffected response to IFN-α/β in heterozygous cells." (PMID 37140667, 2023). "Furthermore, increased phosphorylation of STAT1 suggested transcriptional activation of ISGs, which control viral infection." (PMID 37881429, 2023). "Previous studies have theorized that hsa-miR-146a is overexpressed in many viral diseases, targeting and inhibiting specific genes, such as STAT1, SOCS1/STAT3, TCL1, CXCL4, and NFκB in hepatitis B and C, EBV, human immunodeficiency type-1, and human T-lymphotropic type 1, respectively." (PMID 37233676, 2023). "Apart from this similarity, different virus infection pathways owned their unique genes, with STAT1,RSAD2 and IRF9 in the influenza A pathway,IL-2RA,IL-2RB and CD40 in the HTLV-1 infection pathway, HCFC1, MAP3K7, SOCS3, IRF9, HMGN1, and FAS in the herpes simplex infection pathway." (PMID 35795668, 2022). "In 2001, the first STAT1 deficiency with AD was reported in two kindreds with susceptibility to mycobacterial but not viral diseases." (PMID 36569938, 2022). "To address whether RUNX1 could indirectly modify phosphorylation of IRF3 and STAT1 upon viral infection, we infected the cells with PR8 at an MOI of 5, collected the cells at 3, 6, and 9 h.p.i." (PMID 35248104, 2022). "One explanation is that PKR‐mediated STAT1 activation and ISGs induction directly inhibits viral infection, which may result in less activation of RIG‐I‐TBK1‐IRF3 signaling and less IFN‐β production." (PMID 35312140, 2022).
viral infection (continued). "Moreover, impaired CD8+ T cell expansion in response to viral infections has been reported earlier in STAT4-deficient mouse models, that is also associated with higher STAT1 levels." (PMID 36072585, 2022). "PKR‐mediated STAT1 activation and ISGs induction directly inhibit viral infection, which may result in less RIG‐I‐TBK1‐IRF3 signaling activation and less IFN‐β production." (PMID 35312140, 2022). "Consistent with the quantitative proteomic results, qRT‐PCR results showed that along with a lower level of viral titration, higher levels of ISGs such as Isg15, Oasl2, and Stat1 were detected in livers of WT mice than those from Neurl3−/− mice post‐viral infection." (PMID 35792897, 2022). "STAT1 reduces virus infection and inflammatory responses in infected mice." (PMID 34653236, 2021). "STAT-1 deficient mice do not respond to either type I or type II interferon and are therefore highly susceptible to viral infection." (PMID 33573250, 2021). "Regarding the role of STAT1 in parasitic infections, there is abundant literature indicating the importance of this transcription factor in the defense against intracellular parasitic pathogens and viral infections." (PMID 34684235, 2021). "STAT1 is one of the transcription factors expressed by M1 macrophages can drive activation of interferon stimulating genes and mediate antiviral activity in vivo and in vitro, which are crucial for host defense against virus infections." (PMID 34653236, 2021). "Patients with heterozygous STAT1 GOF mutations usually present with CMC, although some may also suffer bacterial and viral infections, autoimmune manifestations, lymphopenia, cerebral aneurysms, and increased risk of developing tumors." (PMID 33777053, 2021). "In this study, we investigated whether Leu could increase the STAT1 and ISGs expressions to counteract virus infection." (PMID 34367129, 2021). "These previous findings provide the premise to hypothesize that when DUSP1 is knocked down during JCPyV infection in NHAs, viral infection is reduced because STAT1 is translocated to the nucleus, activating ISGs and thus inhibiting JCPyV infection." (PMID 34578413, 2021). "The viral protein VP35 blocks human type I interferons (IFNs) to prevent the DCs from responding to the viral infection, thereby avoiding the nuclear accumulation of signal transducers, activators of transcription 1 (STAT1), and signal transducers in infected cellular targets." (PMID 34944612, 2021). "AD GOF STAT1 mutations lead to defective Th1 and Th17 responses with a reduced production of IFN-γ, IL-17 and IL2, thereby leading to a phenotype of CMC, susceptibility to bacterial and viral infection and autoimmunity." (PMID 34867986, 2021). "STAT1 is a key regulator in IFN signaling pathway during virus infection." (PMID 33242255, 2020). "Importantly, in STAT1-deficient cells (U3A), the ability of USP12 to inhibit viral infection was largely attenuated." (PMID 31899788, 2020). "Indeed, although type 1 IFN predominantly uses the STAT1 pathway, leading to anti-proliferative effects, viral infection induces predominant STAT4 expression and promotes IFNγ." (PMID 33013883, 2020). "Interestingly, viral infection can stimulate strong linear ubiquitination of STAT1 to inhibit IFN-I antiviral signaling." (PMID 32123171, 2020). "However, STAT1 linear ubiquitination was strongly upregulated after 6 h of viral infection, when HOIP expression was substantially induced by viruses." (PMID 32123171, 2020). "STAT1 is a major mediator of the type I interferon response to viral infection." (PMID 31575039, 2019). "Unexpectedly, STAT1 gain-of-function (GOF) mutations are likewise associated with increased susceptibility to infectious diseases, such as chronic mucocutaneous candidiasis, bacterial and viral infections, autoimmune diseases and even cancer." (PMID 31781102, 2019).
viral infection (continued). "The results showed that IPEC-J2 cells treated with Lp-1s could effectively increase STAT1 phosphorylation in the late stage of virus infection." (PMID 31781061, 2019). "However, STAT1 represses whereas STAT4 activates IFNγ expression in T cells during a viral infection." (PMID 31228946, 2019). "This is consistent with observations that mice lacking intact JAK/STAT signaling (IFN receptor or STAT1 knockout mice) are more susceptible to virus infection than wild-type mice." (PMID 29662014, 2018). "To test whether other LY6/uPAR family members enhance viral infection, we generated lentivirus encoding LY6 family members and transduced STAT1-/- fibroblasts with a dose response of viral particles, with input normalized by p24 ELISA." (PMID 30190477, 2018). "In addition, residue 186 played a central role in limiting STAT1 nuclear translocation, as O/03-K186E virus infection resulted in abundant nuclear STAT1." (PMID 29237841, 2018). "To assess whether LY6E could enhance viral infection via transcriptome modulation, we used RNA-Seq to compare gene expression profiles of STAT1-/- fibroblasts expressing an empty vector as a control versus cells expressing LY6E." (PMID 30190477, 2018). "Therefore, it is also notable that available data implies a correlation between viral-induced serine monophosphorylation of STATs (STAT1 and STAT3) and pro-inflammatory responses caused by virus infection." (PMID 29662014, 2018). "Given that NDR1 positively regulates STAT1 expression and facilitates ISGs induction after viral infection, we tested whether NDR1 might prevent HCV infection." (PMID 30018336, 2018). "Mice lacking intact JAK/STAT signaling, such as IFN-receptor or STAT1 knockout mice, are more susceptible to virus infection than wild-type mice." (PMID 29312301, 2017). "Therefore, to address this question, we sought to investigate activation of STAT1 during the viral infection." (PMID 29312239, 2017). "The role of C6 in inhibiting the JAK-STAT pathway during virus infection may be masked to some degree by the effect of VH1 that dephosphorylates STAT1 and STAT2 rapidly after infection." (PMID 27907166, 2016). "STAT1 deficiency in humans is an autosomal recessive immune disorder; null mutations are associated with recurrent bacterial and viral infections indicating impaired NK-cell activities although no detailed information is available so far." (PMID 28149296, 2016). "Furthermore, increased STAT-1 phosphorylation indicates the transcriptional activation of interferon-stimulating genes (ISGs) which involved in controlling viral infection." (PMID 27484768, 2016). "Finally, a study in mice found a role for the signal transducer and activator of transcription 1 (STAT1) transcription factor, a factor known for controlling viral infection, in limiting MuAstV replication." (PMID 28042824, 2016). "During virus infection, TLR-mediated signalling in macrophages triggers the induction of an IFN response, which promotes the production of 25HC mediated by STAT1; in turn this oxysterol can act on multiple levels as a potent paracrine inhibitor of viral infection for a broad range of viruses." (PMID 26880213, 2016). "In HIV infection of cultured cells, the STAT1 inhibitor fludarabine significantly decreased IL-6 expression indicating the importance of STAT1 signalling for IL-6 expression during viral infection." (PMID 25900439, 2015). "Dox-induced STAT1 established protection against virus infections in primary cells and mice." (PMID 24489749, 2014). "Accordingly, STAT1-deficient (STAT1−/−) mice are highly susceptible to viral infections due, in part, to lack of direct antiviral defense mediated by type I IFNs." (PMID 24788809, 2014). "In humans, partial loss of STAT1 activity leads to mycobacterial and viral diseases, although in contrast to cases completely lacking STAT1 such patients are curable." (PMID 24489749, 2014).
viral infection (continued). "Furthermore, we show that spatially and temporally balanced STAT1 expression is essential for host defense against virus infection." (PMID 24489749, 2014). "Moreover, modification of STAT1 to a form) that improves the efficiency of IFN signal transduction can result in improved control of viral infection." (PMID 22574190, 2012). "However, little is known about the mechanism(s) responsible for STAT1-independent protection against viral infections." (PMID 21379341, 2011). "This may also explain how type I IFN can additionally prime cells to respond to a range of other cytokines that use STAT1 (e.g., IL-6, M-CSF, IL-10) and suggests a potential mechanism for the changing levels of STAT1 expression observed during viral infection." (PMID 20436908, 2010). "Notably, cGAS and STING transcripts and proteins were suppressed during WT but not mutant virus infections - even in STAT1-deficient cells - suggesting that Nsp15 contributes directly to their downregulation." (PMID 41880208, 2026). "However, little is currently known about how IL-10 activates STAT1 during viral infections." (PMID 40001503, 2025). "CXCL-9 and CXCL-10 are STAT1-dependent inflammatory factors induced by different cell populations in response to interferons and IL-27, and their expression correlates with the induction of interferon-stimulated genes (ISGs) which promote an antiviral state to control viral infections." (PMID 40711072, 2025). "Interestingly, we identified poly-ubiquitination of STAT1 at lysine 525 during viral infection." (PMID 41213949, 2025). "Notably, JAK inhibitor treatment has previously been shown to increase the degranulation capacity of NK cells, which could contribute to protection against viral infections and cancer in patients with STAT1 GOF." (PMID 36050429, 2023). "Notably, co-IP analysis provided meaningful information that OPRP2 highly induced type I IFN-dependent signaling pathways via STAT1/STAT2 heterodimerization that consequently activated powerful cellular responses to extraneous attacks such as a viral infection." (PMID 35740960, 2022). "Thus, STAT1 is an important target in preventing or treating viral-infection-induced inflammation." (PMID 35563088, 2022). "Notably, underlining the connection between viral infection, IFN production, STAT-1/2 activation, and M1 polarization, it has been found that sixteen enzymes involved in the glycolytic pathway are upregulated by STAT-1, which is typically induced by the virus." (PMID 33815663, 2021). "While AD STAT1 LOF mutated patients suffer from infections with mycobacteria and other macrophage-bound bacteria but do not demonstrate undue susceptibility to viral infections, AR hypomorphic STAT1 LOF mutated patients are prone to both mycobacterial and viral infections." (PMID 33442967, 2021). "Some patients might present first with mild auto-immune features such as autoimmune hypothyroidism, and then later in life during adulthood develop infectious complications such as CMC and severe viral infections with immunophenotypic abnormalities raising a suspicion for STAT1 GOF." (PMID 34867986, 2021). "Susceptibility to predominantly viral infections was observed in TET2, TPP2 and TNFAIP3 patients while chronic mucocutaneous candidiasis (CMC) and mendelian susceptibility to mycobacterial disease (MSMD) were characteristic of STAT1 GOF and IL12RB1 patients, respectively." (PMID 34447369, 2021). "Furthermore, HOIP knockout promoted STAT1 activation during viral infection." (PMID 32123171, 2020). "We further analyzed whether and how viral infection regulates STAT1 linear ubiquitination." (PMID 32123171, 2020). "The only instance of viral infection in murine cells where strong replication and particle production were demonstrated relied on the use of a blasticidin-selectable genome (Jc1-bsd) in immortalized Stat1 knockout MEFs (iMEFs) expressing the human HCV entry factors, miR-122 and mApoE." (PMID 31074414, 2019).
viral infection (continued). "Considering the activation of JAK1 was not different in WT and MHC I-deficient cells during viral infection, we concluded that STAT1 may be the target of MHC I." (PMID 31583257, 2019). "On the other hand, a report about two unrelated infants with homozygous STAT1 deleterious mutations revealed for the first time that complete lack of STAT1 production abolishes not only IFNγ signaling but also IFNα/β response in vivo, which resulted in susceptibility and death after viral infection." (PMID 29892288, 2018). "Furthermore, overexpression of NS2B3 markedly reduced the protein levels of Jak1 but not the levels of STAT1, which consequently inhibited the phosphorylation of Jak1 and STAT1, as well as the translocation of STAT1 from the cytoplasm to the nucleus after viral infection." (PMID 28373913, 2017). "In this tissue, the viral infection triggered a localized release of TNF-alpha and IFN-gamma, culminating in NF-kB- (and possible STAT1)-induced iNOS overexpression." (PMID 41596343, 2026). "The JAK proteins are phosphorylated upon binding of type I IFNs to IFN-α receptor 1 (IFNAR1) and IFNAR2, which then activate transcription factors such as STAT1 and STAT2 to induce transcription of ISGs that respond to viral infections." (PMID 40130878, 2025). "Independently of STAT1, FAH was identified as a host factor that contributes to the control of viral infection, and its metabolite, DMF, exhibited antiviral activity." (PMID 40048440, 2025). "Upon IFNs stimulation or viral infection, IFN binds to cell-surface receptors, activating STAT1, leading to its phosphorylation, dimerization, and translocation to the nucleus, where it regulates gene expression and enhances the cell’s antiviral function." (PMID 40920886, 2025). "In human THP-1 cells, ferrous iron potently attenuated the viral infection-induced expression of IFN-β and the activation of IRF3, TBK1, and STAT1, resulting in the enhancement of viral replication." (PMID 40595467, 2025). "In this study, we reveal that SVA 3Cpro suppresses the IFN-induced response by cleaving and degrading STAT1 and STAT2; this observation was confirmed in the context of virus infection." (PMID 38869319, 2024). "To assess the effect of mSTAT in the viral infection context, we transfected HEK-293T cells with WT STAT1/STAT2 or its mutants for 24 h, followed by SVA infection for 12 h." (PMID 38869319, 2024). "Endogenous STAT1 and STAT2 were precipitated with SVA 3Cpro in the viral infection context, consistent with the results observed in the overexpression assay." (PMID 38869319, 2024). "During viral infection, miR-146a-5p suppresses the production of type-I interferon by targeting not only IRAK2, TRAF6, and IRAK1 but also STAT-1 and IRF-5." (PMID 38787176, 2024). "An interruption to the conjugation of ubiquitin and ISG15, affects IFN signaling, NFκB or signal transducer and activator of transcription 1 (STAT1), and other genes essential for the rapid response against viral infection." (PMID 39599842, 2024). "In contrast, other reports indicate STAT1 and type I IFN induced during viral infections inhibit Treg cell proliferation and activation of Foxp3+ Tregs." (PMID 38085267, 2024). "Collectively, these data suggest that SVA 3Cpro is responsible for cleaving STAT1 and STAT2 in the virus infection context." (PMID 38869319, 2024). "The qRT-PCR results indicated an up-regulation trend for DDX58, STAT1, and MX1, while IRAK1, MAPK11, RELA, and ICAM1 exhibited a down-regulation trend as the duration of the viral infection increased." (PMID 38673764, 2024). "Work by others in CD8+ T cells has shown that reduced levels of STAT1, maintained by STAT4, are required for overcoming the antiproliferative effects of type I IFN during viral infection." (PMID 39560988, 2024). "During acute viral infection, IL6 activates both Stat1 and Stat3, with the latter being required to limit IL2/Stat5-induced Th1 differentiation." (PMID 37275873, 2023).